MICA (MHC class I polypeptide-related sequence A)
Diseases named in the same sentence as MICA in open-access papers (continued):
Sharing a sentence is not in itself a finding about the gene and the disease.
cancer (continued). "However, cancer cells have developed a defense mechanism of shedding MICA from the cell surface, making it difficult for the immune system to recognize it as dangerous." (PMID 36547538, 2022). "Furthermore, TGFβ upregulates expression of NK cell inhibitory receptors while at the same time downregulating activating receptors such as NKp30 and NKG2D or their respective ligands, such as MHC class I polypeptide-related sequence A (MICA), on cancer cells." (PMID 33925968, 2021). "In addition, soluble ligands released by cancer cells, such as MICA/B, bind NKG2D, which blocks the interaction between NK cells and target cells, thus downregulating NKG2D expression on the surface of NK cells and promoting immune evasion." (PMID 34439285, 2021). "In addition, a series of genetic variants in MICA, MICB, NFKBIL1, SLC6A3, CLPTM1L, and TERT have been found to be associated with the susceptibility and prognosis of different cancer types." (PMID 35003220, 2021). "Furthermore, several MICA transmembrane regions, based on the GCT repetitions, have been associated to higher susceptibility to certain types of cancers." (PMID 33868281, 2021). "However, advanced cancers frequently escape this immune mechanism by proteolytic shedding of cell surface-bound MICA and MICB molecules through the coordinate action of ERp5 and several cell surface proteases." (PMID 33789714, 2021). "For the targeting of MICA and MICB in cancer patients, we generated anti-MICA and MICB antibodies, by immunizing mice with recombinant soluble human MICA-Fc recombinant protein or a range of human C1R cells negative for endogenous MICA and MICB expression and engineered to express MICA alleles." (PMID 35967081, 2021). "In addition, the sheddase ADAM-10 mediates the reduction of NKG2D ligand expression on the cancer cell surface by cleaving MICA/B and is involved in the immune escape mechanism, which impairs NK cell recognition." (PMID 34502547, 2021). "Furthermore, TGF-β1/2 siRNA cells showed an increased expression of the NKG2D ligand MICA; higher levels of this ligand on cancer cells together with changes in NKG2D expression resulted in increased NK cell-mediated killing of silenced cells." (PMID 31948072, 2020). "This approach may be applicable to several cancer types that upregulate MICA/B antigens and may have an additive effect with additional treatments." (PMID 32153582, 2020). "Notably, there are previous reports of anti-MICA antibodies generated in cancer patients in the course of disease and/or treatment." (PMID 32582150, 2020). "Moreover, future experiments exploring the effect of PPAPs on cancer cells with dysregulated levels of HLA-E, MICA/B and MHC are also needed." (PMID 32887413, 2020). "Soluble MICA is commonly secreted by cancer cells as an immune evasion mechanism." (PMID 32544282, 2020). "However, cancer shedding of MICA*008 via exosome secretion appears to be one way in which cancers have adapted to circumvent this." (PMID 33352921, 2020). "Therefore, we assessed HSF-1, HSP70 and MICA expression in cervical cancer cells after metformin treatment and also investigated the sensitivity of NK-92 cells to cancer cells." (PMID 32631421, 2020). "Indeed, transient RNAi-mediated silencing of ADAM10 or ADAM17, or both, in distinct cancer cell lines revealed a considerable heterogeneity with regards their role in the proteolytic cleavage of MICA and MICB." (PMID 32269567, 2020). "The combinatorial therapy of CIK cells with MICA-antibody may provide more benefit for cancer patients and deserves to be further investigated." (PMID 32645836, 2020). "The inhibition of MICA/B shedding by URB597 may enhance the immune surveillance of cancer cells, which may explain the antitumor effect of cannabinoid-mediated signaling." (PMID 32968163, 2020).
cancer (continued). "Notably, the preferential expression of MICA/B on cancer stem cells (CSCs) from PDAC cell lines and dissociated primary cancer samples was described to favor the NKG2D-dependent killing of CSCs by NK cells." (PMID 33321719, 2020). "While in other cancers chemotherapy is reported to upregulate NK cell-activating ligands, a comparison of pre- and post-chemotherapy OS tissue sections provided evidence for either unaltered or decreased expression of MICA, CD112, and CD155 after chemotherapy." (PMID 33322371, 2020). "The clinical utility of α3 domain-specific MICA/B antibodies may hold great promise as a new strategy for cancer immunotherapy." (PMID 31387641, 2019). "The clinical utility of therapeutic α3 domain-specific MICA/B antibody may hold great promise as a new strategy for cancer immunotherapy." (PMID 31387641, 2019). "Decreased MICA/B expression may facilitate cancer immune escape from natural killer (NK) cell-mediated cytotoxicity." (PMID 31088566, 2019). "When examining the surface receptor expression on cancer-patient and healthy individuals’ osteoclasts, decreased expression of MHC-class I, CD54, KLRG1, KIR2, and MICA/B could be seen on cancer patients’ OCs as compared to healthy OCs." (PMID 31878338, 2019). "In addition to forming MICA immune complexes, α3 domain-specific antibodies have the potential to enhance MICA density on cancer cells, and impair the release of shed MIC protein." (PMID 31387641, 2019). "Interestingly the usage of these antibodies limited MICA/B shedding in human cancer cells and repressed cancer cell growth in in vivo models." (PMID 31736972, 2019). "Moreover, therapeutic antibodies such as Herceptin have been developed that block proteolysis of the RTK HER2 and similar proteolysis blocking antibodies have been developed for the MICA immune receptor to block cancer cells from evading the immune system." (PMID 31172946, 2019). "However, in the response to hypoxia, advanced cancers can escape NK-mediated killing through shedding of cell surface MICA and MICB molecules." (PMID 31396523, 2019). "In cancer cell lines, MICA cleavage has been mapped to the α3 and stalk domains." (PMID 31387641, 2019). "In addition to prognostic utility, an improved understanding of MICA/B in various cancers types should enable the development of more precise and effective immunotherapies." (PMID 29221214, 2017). "Serum soluble MICA/B represents a potential prognostic marker in various human cancers." (PMID 29221214, 2017). "Therefore, we conducted a systematic review and two meta-analysises to establish pooled estimates for survival outcomes based on sMICA/B serum levels and MICA/B cell surface expression in different types of cancers." (PMID 29221214, 2017). "OS was reported in 10 studies of MICA/B expression in a total of 1,183 cancer patients." (PMID 29221214, 2017). "And serum soluble MICA/B and cancer cell-surface MICA/B are detected by two different methods." (PMID 29221214, 2017). "Mechanistically, the cancer cell-selective induction of MICA could be ascribed to multiple targets potentially encompassing HDAC status and cancer cell metabolism, and is as important as the cancer-specific apoptosis by HDACi58." (PMID 27910927, 2016). "This study demonstrates that MICA expression is strongly influenced by cell-surface adhesion and cell–cell contact and this has implications for understanding the immunopathogenesis of cancer metastasis." (PMID 28154561, 2016). "Serum levels of soluble MICA/B are elevated in patients with various types of cancer." (PMID 25138242, 2014). "However, through shedding of MICA/B, cancer cells can escape this mechanism of immunosurveillance." (PMID 41050431, 2025). "Several other drugs could also increase MICA/B expression by human cancers." (PMID 38882209, 2024).
cancer (continued). "Our in silico approach sets the stage for future investigations in cancer and inflammatory models, where empirical experiments will be pivotal to establish conclusive insights, thus advancing our understanding of the intricate relationship between miRNAs and MICA allelic variability." (PMID 38146340, 2023). "However, it is noteworthy that several cancers exhibit high levels of soluble MICA, which could potentially compete with MICA-bearing NKCEs for binding of NKG2D, thereby reducing their effectiveness." (PMID 37638058, 2023). "Additionally, we also have identified several miRNAs (hsa-miR-20a-5p, hsa-miR-93, hsa-miR-106a-5p, and hsa-mir-106b) that have been previously reported to be upregulated and act as down-regulators of MICA expression in various types of cancer, which supports our prediction approach." (PMID 38146340, 2023). "One important highlight is the observation that HDAC inhibition could improve cancer cells’ immune response via the regulation of the expressions of tumor antigens, including CD40, CD80, CD86, MHC, ICAM-1 and MICA/B, which drive the elimination of cancer cell proliferation through the immune system." (PMID 35158821, 2022). "Consequently, cancer cells must acquire specific mechanisms to counterbalance NK cells killing, by reducing the engagement with stimulating receptors, as induced by membrane-shedding of MICA/B, or by stimulating the expression of inhibitory molecules." (PMID 36230808, 2022). "However, several molecules have been shown to be associated with the proteolytic shedding of MICA and MICB, leading to the immune escape in advanced cancers, such as disulfide isomerase (ERp5) and ADAM (a disintegrin and metal-loproteinase) proteins and MMPs (matrix metalloproteinases)." (PMID 32645836, 2020). "Indeed, accumulating evidence suggest that changes in levels of NKG2D ligands, mainly MICA, as well as an increase of immune checkpoint inhibitors (e.g., PD-L1) and other inhibitory ligands on cancer cells significantly contribute to TGF-β-mediated suppression of NK cell activity." (PMID 31948072, 2020). "Hence, we asked whether MICA shedding and its functional implications for cancer immunosurveillance can also be studied in MICAgen mice." (PMID 32582150, 2020). "In line with this hypothesis, restoration of membrane-bound MICA (mMICA) levels in HCC cells augmented natural killer (NK) cell-mediated anti-cancer activity in our and other groups’ studies, proving the concept of natural killer group 2D (NKG2D) signaling-mediated immunotherapy." (PMID 29721164, 2018). "As the prognostic role of MICA/B seems to be substantially different according to cancer site, the overall pooled analysis of all types of cancer may have been highly dependent on the relative proportion of each specific type of cancer." (PMID 29221214, 2017). "Combinational use of proteinase inhibitors that block MICA/B cleavage or use of chemotherapeutic drugs that can also suppress proteinase expression may further improve the therapeutic outcome of immunotherapy for pancreactic cancer." (PMID 21605422, 2011). "MICA and MICB expression levels in digestive system malignant tumors are generally higher than in relatively normal tissues." (PMID 40563539, 2025). "In a few clinical studies, the potential roles of ADAMs and MHC class I polypeptide-related sequence A(MICA), an NKG2DL, as cancer-screening biomarkers have been demonstrated." (PMID 39755747, 2025). "Apart from the IRE1α axis, the PERK–ATF4–CHOP pathway upregulates explicitly the expression of NKG2DL (mainly MICA and ULBP2) in cancer cells, enhancing their binding to NKG2D and subsequently activating NK cells for cancer cell destruction." (PMID 40547943, 2025). "Major histocompatibility complex class I related chain A (MICA) is an important and stress-induced ligand of the natural killer group 2 member D receptor (NKG2D) that is expressed in various cancer cells." (PMID 40726981, 2025).
cancer (continued). "Cancer cells which shed their MHC class I chain-related protein A (MICA) and protein B (MICB) can exhibit immune escape properties and ultimately promote rapid cancer progression." (PMID 38726000, 2024). "Therefore, we tested whether soluble MICA (shed from the cell surface by proteolytic cleavage, found at levels up to 1–50 ng/mL in the sera of patients with cancer including AML, and representing a dominant soluble NKG2D ligand in AML patients) and/or CD33 could interfere with CC-96191 cytotoxicity." (PMID 38473239, 2024). "In HCC, NK cells are key players in antitumor immunity, primarily due to their capacity to recognize stress-induced ligands such as MHC class I-related chain A/B (MICA/B) and UL16-binding proteins (ULBPs) on the surface of cancer cells." (PMID 39502703, 2024). "Previous studies have demonstrated that histone acetylation regulates NKG2D ligand expression such as MICA, MICB, and ULBPs, which are critical for the activation of natural killer (NK) cells and immune surveillance against cancer cells." (PMID 39161385, 2024). "Elevated serum levels of soluble MICA and soluble CEACAM-5 and CEACAM-6 have been correlated with impairment of NK cell activity, cancer progression and metastasis." (PMID 36991390, 2023). "This review summarizes the novel mechanism of immune escape in the ncRNA-related MICA/NKG2D pathway mediated by NK cells and cancer cells." (PMID 37784183, 2023). "It is well recognized that many human cancers, including ccRCC, express the MHC class I chain-related polypeptide A (MICA) protein that serves as a ligand for the activating NK group 2D (NKG2D) receptor on NK cells." (PMID 38067341, 2023). "We found the stress MICA/MICB proteins to be downregulated in patients on bevacizumab, and low levels correlated with more prolonged survival, as found in other cancers." (PMID 36968223, 2023). "Modification of MICA with poly-N-acetyllactosamine reduces its affinity for NKG2D on NK cells, which allows cancer cells to evade NK-mediated cell death." (PMID 37110670, 2023). "One of the substrates of C2GnT is MHC class I-related chain A (MICA), a ligand expressed by cancer cells for an NK-activating receptor (NKG2D)." (PMID 37110670, 2023). "We searched for all relevant publications in the PubMed, Scopus and Web of Science database using the keywords ncRNA, MICA, NKG2D, cancer, and miRNAs." (PMID 37784183, 2023). "Combining anti-MICA/B antibodies and immune modulators can activate NKG2D-dependent NK cells and CD8+T cell response in cancers, including HCC." (PMID 36765808, 2023). "The downregulation of miR-146b-5p increased MICA and NKG2D expression in PTC and cancer cells, respectively." (PMID 37784183, 2023). "MSCs induce significant upregulation of MHC class I chain-related protein A (MICA) and poliovirus receptor (PVR) levels on these cancer cells." (PMID 36768145, 2023). "Second, most immuno-stimulators, such as MICB, MICA, CD80, ICOS, CD27, and various TNFSFs (all P < 0.05), were expressed at higher levels in PTPRD/PTPRT mutant cancers, compared with the WT." (PMID 36248841, 2022). "MICA, one of the main ligands to NKG2D receptor, has been considered an immunological target due to its participation in immune evasion mechanisms in cancer, including GC." (PMID 33868281, 2021). "TM4SF5 expression in cancer cells downregulated stimulatory ligands and receptors for NK cell cytotoxicity, including SLAMF6, SLAMF7, MICA/B, and others." (PMID 34921636, 2021). "These drugs also upregulate the expression of MHC class I polypeptide-related sequence A (MICA) and heat shock protein 70 (HSP70) on cancer cells through the phosphatidylinositide 3-kinase/protein kinase B pathway leading to NK cell activation." (PMID 34025641, 2021). "We previously reported that radicicol and radicicol-formulated nanoparticles optimally induce the expression of the NKG2D ligands MICA/B and MULT-1 in human and murine cancer models, respectively, compared to other pharmaceutical inhibitors of Hsp90." (PMID 34926577, 2021).
cancer (continued). "Both Vδ1 and Vδ2 T cells can detect MICA/B and ULBP ligands on cancer cells via interaction with their NKG2D receptor, facilitating their activation and leading to the release of perforin and granzyme B." (PMID 34944832, 2021). "The mechanisms employed for evading immune surveillance by cancer cells include among others down regulation of surface expression of NKG2D ligands ULBP1, ULPB2 and MICA." (PMID 32592353, 2020). "Among them ADAM10, a catalytically active member of the ADAM family of proteases, is involved in the cleavage of MICA, MICB, and ULBP-2 molecules in various types of cancer cells." (PMID 32269567, 2020). "Among them, ADAM10 cleaves MICA, MICB, and ULBP-2 in different types of cancer cells and its increased expression correlates with cancer progression in MM, malignant pleural mesothelioma, oral squamous cell carcinoma, and gastric cancer." (PMID 32570952, 2020). "ADAM9 was reported to facilitate the cancer progression by mediating ectodomain shedding of HB-EGF and major histocompatibility complex class I-related chain A (MICA)." (PMID 32637415, 2020). "Our results reveal a new strategy for cancer immunotherapy by harnessing the MICA/B-NKG2D signaling pathway, even in the presence of immunosuppressive soluble MICA, which is prevalent in multiple cancers." (PMID 31387641, 2019). "Interaction of the cancer cell surface stress proteins, MHC class I chain-related molecule A and B (MICA/B) or UL16 binding protein 1-6 (ULBP-1/6) with the NKG2D receptor on NK cells also triggers NK cell cytolytic action." (PMID 31396523, 2019). "In cancer patients, MICA shedding is predicted to antagonize ADCC activity by serving as an antibody sink and reducing surface MICA expression." (PMID 31387641, 2019). "The binding of MICA/MICB to NKG2D receptors triggers NK cell-mediated cytotoxicity and enables them to eliminate cancer cells." (PMID 31234517, 2019). "Our results showed that strong cell-surface expression (2+ and 3+) of MICA and ULBP2 was detected in about 68 and 72% of the cancer tissues, respectively." (PMID 31288857, 2019). "MicroRNAs (miRNA or miR) were the first molecules described to impair the expression of the NKG2D ligands MICA, MICB and ULBP2 in cancer cells on mRNA level." (PMID 30254634, 2018). "This allows the proteolytic cleavage of MICA by proteases, including ADAM10, ADAM17 and MMP14, which are overexpressed in cancer cells." (PMID 30597841, 2018). "It has been widely reported that low cell surface expression of MICA/B or elevated sera levels of soluble MICA and MICB correlate with metastasis in different types of cancer." (PMID 30597841, 2018). "Therefore, MICA/B and sMICA/B, reflecting the cancer cell centric biological behavior and tumor immune surveillance status, could be a potential prognostic biomarker of cancer patients." (PMID 29221214, 2017). "The MHC class I chain related-protein A (MICA) and B (MICB) are cancer cell-surface molecules that reflect both cancer cell-centric biological behavior and host immune status." (PMID 29221214, 2017). "In this context, we showed that treatment of MM cells with the STAT3 inhibitor STA-21 or with the JAK2-specific inhibitor AG490 can increase MICA expression, thus confirming the repressive action of STAT3 on this gene also in this type of cancer cells." (PMID 26161387, 2015). "We observed that infection of cancer cells with the oncolytic virus, VSV, leads to an induction of mRNA expression of the NKG2D-ligand, MICA." (PMID 21857986, 2011). "Therefore, an antibody targeting MICA α3 was synthesized to prevent the proteolysis of MICA and MICB from cancer cells, thus allowing the binding of NK cell activating receptor, NKG2D with MICA/B to activate cytotoxic NK cells." (PMID 38726000, 2024).